RPS27AP5 (ribosomal protein S27a pseudogene 5)
Synonyms: RPS27A_1_141
Gene: Processed pseudogene on chromosome 1 (192,716,183 to 192,716,653, forward strand). Ensembl gene ENSG00000231767.
Genetic constraint (gnomAD): Loss-of-function variants: 0 observed, 0.0749 expected, observed/expected ratio (o/e) 0, 90% interval 0 to 1.89. That is too few expected variants to judge how well the gene tolerates losing a copy. Missense variants: 4 observed, 3.79 expected, observed/expected ratio (o/e) 1.06, 90% interval 0.5 to 1.86. Synonymous variants: 0 observed, 1.28 expected, observed/expected ratio (o/e) 0, 90% interval 0 to 1.63.